RIOX1 (ribosomal oxygenase 1)
Description:
Oxygenase that can act as both a histone lysine demethylase and a ribosomal histidine hydroxylase. Specifically demethylates 'Lys-4' (H3K4me) and 'Lys-36' (H3K36me) of histone H3, thereby playing a central role in histone code (By similarity). Preferentially demethylates trimethylated H3 'Lys-4' (H3K4me3) and monomethylated H3 'Lys-4' (H3K4me1) residues, while it has weaker activity for dimethylated H3 'Lys-36' (H3K36me2) (By similarity). Acts as a regulator of osteoblast differentiation via its interaction with SP7/OSX by demethylating H3K4me and H3K36me, thereby inhibiting SP7/OSX-mediated promoter activation (By similarity). Also catalyzes demethylation of non-histone proteins, such as CGAS: demethylation of monomethylated CGAS promotes interaction between CGAS and PARP1, followed by PARP1 inactivation (By similarity). Also catalyzes the hydroxylation of 60S ribosomal protein L8 on 'His-216', thereby playing a role in ribosome biogenesis. Participates in MYC-induced transcriptional activation.
Synonyms: hsNO66; ROX; C14orf169; MAPJD; NO66; FLJ21802; JMJD9; URLC2
Tractability: Small molecule: a structure with a bound ligand is known. PROTAC: ubiquitination databases record sites on it.
Gene: Protein-coding gene on chromosome 14 (73,490,933 to 73,493,394, forward strand). Ensembl gene ENSG00000170468.
Subcellular location: Nucleus, nucleolus; Nucleus, nucleoplasm
Subcellular location (Human Protein Atlas): Nucleoli rim
Pathways (Reactome):
Metabolism of proteins: Protein hydroxylation
Gene Ontology:
Molecular function: 2-oxoglutarate-dependent dioxygenase activity; peptidyl-histidine dioxygenase activity; protein binding; protein demethylase activity; histone H3K36 demethylase activity; histone H3K36me/H3K36me2 demethylase activity; histone H3K4 demethylase activity; histone H3K4me/H3K4me2/H3K4me3 demethylase activity; iron ion binding
Biological process: negative regulation of DNA-templated transcription; negative regulation of osteoblast differentiation; protein hydroxylation; chromatin remodeling; regulation of DNA repair
Cellular component: nucleolus; nucleoplasm; nucleus
Genetic constraint (gnomAD): Loss-of-function variants: 33 observed, 40.93 expected, observed/expected ratio (o/e) 0.81, 90% interval 0.61 to 1.08. The upper end of that interval is the gene's LOEUF score, 1.08, which puts it in group 4 of 6, group 1 being the genes least tolerant of losing a copy. Missense variants: 821 observed, 800.41 expected, observed/expected ratio (o/e) 1.03, 90% interval 0.97 to 1.09. Synonymous variants: 387 observed, 355.98 expected, observed/expected ratio (o/e) 1.09, 90% interval 1 to 1.18.
Homologues: Orthologues: macaque RIOX1 (96% identical), pig RIOX1 (92% identical), dog RIOX1 (83% identical), guinea pig RIOX1 (79% identical), rabbit RIOX1 (78% identical), rat Riox1 (77% identical), mouse Riox1 (76% identical), zebrafish riox1 (42% identical), tropical clawed frog riox1 (41% identical), Drosophila melanogaster NO66 (31% identical), Caenorhabditis elegans jmjc-1 (28% identical). Paralogues in human: RIOX2 (22% identical).
Diseases named in the same sentence as RIOX1 in open-access papers:
RIOX1 is named in the same sentence as 5 diseases in open-access papers, as found by Europe PMC text mining. Sharing a sentence is not in itself a finding about the gene and the disease. The quoted sentences say what the papers report.
cancer (1 paper, 2022). A tumor composed of atypical neoplastic, often pleomorphic cells that invade other tissues. "An example of an unannotated gene with multiple supportive peptides detected in NHP is RIOX1, which is classified as a pseudogene in Ensembl (gorGor4), and it is absent in RefSeq (gorGor6) despite its importance in cancer research." (PMID 35840341, 2022).
RIOX1 also shares sentences with these, for which no sentence is quoted: breast carcinoma (1 paper); lung adenocarcinoma (1); osteosarcoma (1); prostate carcinoma (1).